PPARG (peroxisome proliferator activated receptor gamma)
Diseases named in the same sentence as PPARG in open-access papers (continued):
Sharing a sentence is not in itself a finding about the gene and the disease.
COVID-19 (46 papers, 2020 to 2025). A disease caused by infection with severe acute respiratory syndrome coronavirus 2. "Overall, these results suggest that CALCA, TNF, and PLAT are strongly associated with COVID-19, while PPARG has a relatively weaker association." (PMID 40766923, 2025). "Following these studies, the recent emerging literature has also reported that activation of PPARα, PPARβ/δ, and PPARγ is inversely related to pulmonary fibrosis caused by chronic inflammation in COVID-19 patients." (PMID 36875108, 2023). "This suggests that PPARG may also play a potential role in the pathophysiological mechanisms underlying the comorbidity of COVID-19 and OSA." (PMID 38443855, 2024). "Additionally, the involvement of PPARG in cellular signaling pathways related to COVID-19 severity and hepatolenticular degeneration underlines its significance beyond traditional signaling networks." (PMID 38505269, 2024). "The natural compound γ-oryzanol may also serve as an adjunctive therapy to reduce the cytokine storm associated with COVID-19; the material stimulated PPARγ to modulate oxidative stress and the inflammatory response in adipose tissues." (PMID 36831317, 2023). "Moreover, curcumin is a natural ligand of peroxisome proliferator-activated receptor-gamma (PPAR-γ) and can reduce cytokine production, suggesting that it may play a role in protecting against lung injury associated with COVID-19." (PMID 34064950, 2021). "PPARγ has an immunomodulatory function and plays a role in the resolution of inflammation, its upregulation in nonsurvivors may be a hallmark of nonresolved inflammation in condition of lipid depletion which is characteristic of severe COVID-19." (PMID 34944005, 2021). "In this regard, it has been suggested that activation of PPARγ during COVID-19 can reduce the circulating levels of TNF-α, IL-1, and IL-6 in the innate immune cells such as macrophages and monocytes through interaction with NF-κB." (PMID 36875108, 2023). "Cannabidiol working via PPARγ is proposed as a therapeutic approach for the severe form of COVID-19." (PMID 36831317, 2023). "This research also showed that, out of thirteen targets, the top six (IL-6, PPARG, MAPK3, PTGS2, ICAM1, and MAPK1) are likely to be implicated in the anti-COVID-19 effects of Kochiae Fructus’ active phytomolecules." (PMID 35992697, 2022). "The top six anti-COVID-19 core targets, IL-6, PPARG, MAPK3, PTGS2, ICAM1, and MAPK1, were molecularly docked with the three key active phytomolecules of Kochiae Fructus." (PMID 35992697, 2022). "Recent studies have also highlighted the possible role of PPARγ agonists as modulators of inflammatory and immunomodulatory drugs by targeting the cytokine storm in COVID-19 patients." (PMID 33927728, 2021). "To date, few studies have focused on the potentially interesting link between PPARγ agonists and the development of COVID-19." (PMID 33927728, 2021). "In contrast, PPARγ is upregulated in COVID-19 patient PBMC and SARS-CoV infection in Vero E6 cells (GSE30589)." (PMID 34407143, 2021). "Together, these findings establish the COVID-19-induced PPARG-anxiety pathway." (PMID 40766923, 2025). "Cannabinoids may block viral entry, modulate immune responses (e.g., suppressing pro-inflammatory cytokines via CB2/PPARγ activation), and alleviate COVID-19-related psychological stress." (PMID 40870742, 2025). "Collectively, these observations point to PPARγ as a potential therapeutic target for COVID-19." (PMID 36842152, 2023). "Moreover, several recent studies also reported that the reduction in PPARγ and PPARα is directly related to acute pulmonary inflammation in COVID-19 and the shift of the disease from mild to severe and, finally, death." (PMID 36875108, 2023).
COVID-19 (continued). "A study employing a public database on subjects with type 2 diabetes and COVID-19, along with animal studies, revealed that the PPARγ agonist pioglitazone may ameliorate acute lung injury and SARS-CoV-2-mediated hyperinflammation." (PMID 36831317, 2023). "In our analysis, FOXC1, GATA2, YY1, and PPARG may play a role in the development of COVID-19 and IS." (PMID 37184686, 2023). "For these reasons, pharmacological agents increasing the ACE2 expression, such as statins and PPARγ agonists, could be beneficial in the treatment of COVID-19." (PMID 35053112, 2022). "Some network pharmacology studies also found that PPARG may be a key therapeutic target for COVID-19." (PMID 36119022, 2022). "Interestingly, a recent study proposes PPARα and PPARγ agonists as adjuvants for COVID-19 vaccine, thanks to their ability to enhance both B and T memory cells through different mechanisms." (PMID 35053112, 2022). "For instance, PPARG shows low activity for COVID-19 patients." (PMID 34603282, 2021). "SARS-CoV-2 changes lipid profile in the lung epithelial cells by interfering in PPARα and PPARγ expression or activity, culminating in lipotoxicity, which became these molecules an attractive potential therapeutic target in COVID-19 patients." (PMID 33716771, 2021). "We have identified gene clusters associated with CRC, COVID-19, and biochanin A. Bioinformatic analysis further showed the involvement of six core targets of biochanin A in the treatment of CRC/COVID-19, including EGFR, CCND1, IL2, IL1A, IL6R, and PPARG." (PMID 34931923, 2021). "Likewise, these lipid-related modifications are in agreement with our previous finding that in patients with severe COVID-19, alveolar monocytes/macrophages demonstrate repression of PPARγ, a key regulator of lipid storage and metabolism." (PMID 34225749, 2021). "Furthermore, recent studies have highlighted the interesting role of PPARγ agonists as modulators of inflammatory and immunomodulatory drugs through the targeting of the cytokine storm in COVID-19 patients." (PMID 33927728, 2021). "This renders the glycemic control in these patients an important challenge and begs the question whether the use of anti-diabetics, such as insulin and PPARγ agonists, should be used in COVID-19 patients." (PMID 32930095, 2020). "Therefore, modulation of peripheral IR by PPARγ agonists in virtue of their anti-inflammatory activity may reduce COVID-19 severity in T2DM patients." (PMID 36355535, 2022). "Pioglitazone and rosiglitazone are peroxisome proliferator activated receptor gamma (PPAR-γ,) agonists (thiazolidinediones) that also have anti-inflammatory activities in COVID-19 patients and have been suggested for treatment." (PMID 36983871, 2023). "Thus, activating PPARG with an agonist might be a potential COVID-19 therapeutic modality." (PMID 35992697, 2022). "In contrast, many TFs were identified specifically as the top TFs in COVID-19 patients’ lung cell types, including SMAD3 in ciliated cells, NFKB1 and JUN in dendritic cells, PPARG in macrophage/monocyte cells, and STAT3 in T cells." (PMID 35458567, 2022). "The potential mechanism of action of HXZQ for COVID-19 is inhibiting SARS-CoV-2 replication, improving immune, and anti-inflammatory, mainly by acting on 3CLpro, PTGS2, AR, HSP90AB1, CAMSAP2, PPARG, NOS2, and other targets." (PMID 36388945, 2022). "The PPI network analysis reveals that multiple targets, including IL-6, PPARG, MAPK3, PTGS2, ICAM1, MAPK1, etc., are involved in the anti-COVID-19 effects of Kochiae Fructus’ active phytomolecules." (PMID 35992697, 2022). "From 11 healthy cell-type TRNs and 8 COVID-19 cell-type TRNs, we identified 8 unique central TFs, FOXP1, RUNX1, FOS, SMAD3, JUN, NFKB1, PPARG, and STAT3." (PMID 35458567, 2022). "The results indicated that both PPARγ and PPARα are downregulated, while SOX17 and RUNX1 gets upregulated in COVID-19 patients." (PMID 34407143, 2021).
COVID-19 (continued). "In our analysis, we identified two target gene clusters of biochanin A including inflammatory genes (IL1A, IL2, and IL6R) and cell proliferation genes (CCND1, PPARG, and EGFR) relevant to the treatment of CRC/COVID-19." (PMID 34931923, 2021). "All genes (PPARG, CD36, STAB1, ITGAV, and ANXA2) downregulated in surviving patients with COVID-19 are related to cholesterol homeostasis." (PMID 34944005, 2021). "Using the network pharmacology approach, we identified two clusters of genes involved in immune response (IL1A, IL2, and IL6R) and cell proliferation (CCND1, PPARG, and EGFR) mediated by biochanin A in CRC/COVID-19 condition." (PMID 34931923, 2021). "Evidence has highlighted the fact that PPARγ agonists can increase ACE2 expression, suggesting a possible role for PPARγ agonists in the treatment of COVID-19." (PMID 33927728, 2021). "Taken together, these findings establish that the alterations in PPARG and TNF expression prompted by COVID-19 may also contribute to the decline in cognitive function associated with anxiety." (PMID 40766923, 2025). "Given that Jun, PPARG, and STAT3 are the top TFs from COVID-19 patients’ TRNs, these identified drugs may be candidates for reducing SARS-CoV-2 infection for these cell types." (PMID 35458567, 2022). "In summary, the expression patterns of CD36, GLUT2, IRS1, IRS2, PDX1, and PPARG in the pancreas were altered upon SARS-CoV-2 infection, implying that islet function may be compromised in patients with COVID-19." (PMID 35343389, 2022). "Our results showed 13 potential targets of biochanin A; the molecular interaction network analysis using Cytoscape further highlighted the involvement of six core targets of biochanin A, EGFR, CCND1, IL2, IL1A, IL6R, and PPARG, for the treatment of CRC/COVID-19." (PMID 34931923, 2021). "Interestingly, the decrease in PPARγ expression during SARS-CoV-2 infection, in addition to being positively related to the occurrence of hyperinflammation, also leads to insulin resistance in COVID-19 patients." (PMID 36875108, 2023). "Furthermore, COVID-19 has more negative clinical consequences for obese people because clinical trials indicate that the serum levels of PPARγ are lower in obese people." (PMID 36875108, 2023).
psoriasis (45 papers, 2008 to 2026). An autoimmune condition characterized by red, well-delineated plaques with silvery scales that are usually on the extensor surfaces and scalp. "Recently, PPARγ agonists have been shown to be effective antipsoriatic agents by reducing the keratinocyte hyperplasia associated with psoriasis." (PMID 20508724, 2010). "Research in psoriasis models has demonstrated that IL-17 can directly inhibit PPARγ expression in human keratinocytes, disrupting lipid barrier function." (PMID 41451331, 2025). "In psoriasis, the activation of PPARγ regulates the inflammatory response by reducing the expression and suppressing the genes of adhesion molecules." (PMID 39398333, 2024). "PPARγ stimulation in rodents has been shown to ameliorate several inflammatory diseases, such as atopic dermatitis, psoriasis and acne vulgaris." (PMID 35324426, 2022). "ZNF384 is a potential therapeutic target for psoriasis and AD by regulating PPARG, ZNF415, HLX, and ANHX." (PMID 35669784, 2022). "Our work proposed that STFs (PPARG, ZFPM2, ZNF415, HLX, and ANHX) mediate the initiation of chronic inflammation and metabolic disorders that increase the risk of developing AD in the psoriasis population." (PMID 35669784, 2022). "Interesting that ozonated autohemotherapy (OAHT) treatment also elevated PPARγ expression in CD4+ T cells of patients with psoriasis and decreased patients’ PASI scores." (PMID 34445309, 2021). "FOSL1 was reported to have high level of expression in human psoriasis tissues and be able to inhibit PPARγ directly." (PMID 34445309, 2021). "Recently, low PPARγ expression in CD4+ T cells from 12 psoriasis patients than in healthy controls was reported." (PMID 34445309, 2021). "Accordingly, a novel and specific PPARγ modulator was proven to be anti‐inflammatory and anti‐proliferative and to restore differentiation in a psoriasis‐like mouse model." (PMID 33683743, 2021). "In the CD3+ T-cells of psoriasis patients, the expression level of PPARγ was reduced in 3.4 ± 0.4 times and FOXP3—in 5.4 ± 0.16 times compared to healthy volunteers." (PMID 34445309, 2021). "As far as psoriasis is an inflammatory skin disease characterized by epidermal hyperproliferation and abnormal keratinocyte differentiation, proteins involved in PPARγ signaling can be considered as potential targets for treatment." (PMID 34445309, 2021). "Although information on PPARγ is contradictory in AD, it was shown to be consistently reduced in psoriasis." (PMID 33683743, 2021). "In human studies, systemic PPARγ agonists have shown clinical activity in psoriasis, atopic dermatitis, and cicatricial alopecia." (PMID 34445339, 2021). "The alignment of our preliminary experimental results with microarray data and PPI network analysis shows that the reconstructed model of PPARγ-downregulated signaling in psoriasis can be useful for further research." (PMID 33133175, 2020). "We combined experimental results and network functional analysis to reconstruct the model of PPARγ-downregulated signaling in psoriasis." (PMID 33133175, 2020). "PPARβ/δ activation, which can be antagonistic to PPARγ, has been shown in psoriasis skin, and activation of PPARβ/δ contributed to a psoriasis-like mouse model of disease." (PMID 22957057, 2012). "An increased expression of PPARβ/δ and a decreased expression of PPARα and PPARγ were observed in the lesional skin of patients with psoriasis and atopic dermatitis." (PMID 20706605, 2010). "A great improvement of skin lesions and also of psoriatic arthritis had been initially documented in patients with psoriasis treated with the oral PPARγ activators troglitazone or pioglitazone." (PMID 20706605, 2010). "Both data sets confirm highly significant upregulation of PPARβ/δ in psoriatic skin whereas both PPARα and PPARγ are downregulated, consistent with the notion that PPARβ/δ acts antagonistically to PPARγ in psoriasis, as previously proposed." (PMID 20300524, 2010).
psoriasis (continued). "Conversally, PPARγ inhibits STAT3 which, when overexpressed, induces Wnt5a and causes a psoriasis-like phenotype in vivo." (PMID 19399181, 2009). "So far, PPARγ activation in patients has proven efficient to treat psoriasis, but other therapeutical applications remain to be explored and defined, particularly in the field of carcinogenesis." (PMID 19125181, 2008). "This suggests that the metabolic abnormalities in psoriasis may involve similar regulatory mechanisms, particularly in the pathways regulated by PPARG and AMPK." (PMID 39239353, 2024). "The PPARG gene may increase the incidence of AD in patients with psoriasis by activating a positive feedback loop leading to excessive inflammation and metabolic disorder." (PMID 37274215, 2023). "Above all, the cross-talk between metabolic disorders and inflammation could explain how PPARG affects psoriasis and AD." (PMID 35669784, 2022). "Experimental data we obtained support our model and the hypothesis that in psoriasis low level of PPARγ activity stimulates IL17 synthesis because STAT3 and RORC became less suppressed." (PMID 34445309, 2021). "Therefore, PPARγ can impede the progress of psoriasis, downregulating the expression of proinflammatory genes in a ligand-dependent manner, counteracting the activity of transcription factors." (PMID 34445309, 2021). "In the last work we build the model that describes a hypothesis that low activity of PPARγ signaling may promote psoriasis." (PMID 34445309, 2021). "PPARγ agonists were also effective in a mouse model of psoriasis." (PMID 34445339, 2021). "Can players of PPARG signalling be considered as drug targets for psoriasis treatment?" (PMID 34445309, 2021). "To check the hypothesis, we measured the expression of these genes altogether with PPARγ on the mRNA level in the skin of patients with psoriasis before and after low-intensity laser treatment." (PMID 33133175, 2020). "We hypothesize that the expression of IL17, STAT3, FOXP3, and RORC and FOSL1 genes in psoriatic skin is correlated with the level of PPARγ expression, and they belong to the same signaling pathway that regulates the development of psoriasis lesion." (PMID 33133175, 2020). "In this work, we tested the hypothesis that PPARγ signaling when downregulated may promote psoriasis." (PMID 33133175, 2020). "Within the framework of the model validation, we hypothesize that signaling related to repressed PPARγ activity is correlated with the development of psoriasis." (PMID 33133175, 2020). "Since psoriasis is thought to occur as a result of deregulated T-cell function, it is interesting that both PPARγ and PGE2 act as T-cell and dendritic cell immunosuppressants and that topical application of PGE2 has been shown to result in clinical improvement of psoriatic lesions." (PMID 20508724, 2010). "However, PPARγagonists thiazolidinediones efficiently normalized skin homeostasis whenorally administrated to patients suffering from psoriasis, suggesting thattheir beneficial effects are most likely due to systemic anti-inflammatoryfunctions of PPARγ." (PMID 19125181, 2008). "An mRNA profiling analysis of skin biopsies from patients with atopic dermatitis and psoriasis revealed that PPARα and PPARγ are downregulated in the itchy skin regions of psoriasis patients, while PPARα remains unchanged in patients with atopic dermatitis and PPARγ increases by 24%." (PMID 36552866, 2022). "In summary, this work may form the basis for future investigations studying the impact of abrogation of IL‐1β signalling on PPARγ and its effects on normalization of barrier homeostasis in common inflammatory skin disorders such as atopic dermatitis and psoriasis." (PMID 33683743, 2021). "Furthermore, PPARγ activation was shown to ameliorate skin lesions in patients with psoriasis." (PMID 33683743, 2021). "Among these, four genes, PPARG, ZFPM2, ZNF415, and HLX, were down-regulated and ANHX upregulated in psoriasis and AD." (PMID 35669784, 2022).